GNMT (glycine N-methyltransferase)
Description:
Catalyzes the methylation of glycine by using S-adenosylmethionine (AdoMet) to form N-methylglycine (sarcosine) with the concomitant production of S-adenosylhomocysteine (AdoHcy), a reaction regulated by the binding of 5-methyltetrahydrofolate. Plays an important role in the regulation of methyl group metabolism by regulating the ratio between S-adenosyl-L-methionine and S-adenosyl-L-homocysteine.
Synonyms: HEL-S-182mP
Tractability: Small molecule: it has a high-quality binding pocket. PROTAC: its protein half-life has been measured; a small molecule that binds it is known.
Target class: Enzyme; Transferase
Safety:
Unwanted effects reported when the protein is acted on. In parentheses: how it was acted on, where the effect was seen, and who reports it.
hematological toxicity (source: ClinPGx)
Gene: Protein-coding gene on chromosome 6 (42,960,690 to 42,963,883, forward strand). Ensembl gene ENSG00000124713.
Subcellular location: Cytoplasm
Subcellular location (Human Protein Atlas): Cytosol
Pathways (Reactome):
Metabolism: Glyoxylate metabolism and glycine degradation; Metabolism of ingested SeMet, Sec, MeSec into H2Se
Developmental Biology: Developmental Lineage of Pancreatic Acinar Cells
Gene Ontology:
Molecular function: glycine binding; glycine N-methyltransferase activity; identical protein binding; protein binding; S-adenosyl-L-methionine binding
Biological process: protein homotetramerization; S-adenosylmethionine metabolic process; one-carbon metabolic process; regulation of gluconeogenesis
Cellular component: cytosol; cytoplasm
Genetic constraint (gnomAD): Loss-of-function variants: 26 observed, 27.16 expected, observed/expected ratio (o/e) 0.96, 90% interval 0.7 to 1.33. The upper end of that interval is the gene's LOEUF score, 1.33, which puts it in group 5 of 6, group 1 being the genes least tolerant of losing a copy. Missense variants: 365 observed, 380.82 expected, observed/expected ratio (o/e) 0.96, 90% interval 0.88 to 1.04. Synonymous variants: 163 observed, 152.76 expected, observed/expected ratio (o/e) 1.07, 90% interval 0.94 to 1.22.
Gene-disease validity (ClinGen):
ClinGen rates the evidence that GNMT causes each of these diseases.
glycine N-methyltransferase deficiency (autosomal recessive): Limited. Glycine N-methyltransferase deficiency (GNMT deficiency) is a very rare condition characterized by persistent and isolated excess levels of methionine in the blood (hypermethioninemia).
Homologues: Orthologues: chimpanzee GNMT (100% identical), macaque GNMT (99% identical), pig GNMT (95% identical), rabbit GNMT (94% identical), mouse Gnmt (92% identical), guinea pig GNMT (89% identical), dog GNMT (85% identical), rat Gnmt (80% identical), tropical clawed frog gnmt (77% identical), zebrafish gnmt (73% identical), Drosophila melanogaster Gnmt (56% identical).
Diseases named in the same sentence as GNMT in open-access papers:
GNMT is named in the same sentence as 81 diseases in open-access papers, as found by Europe PMC text mining. Sharing a sentence is not in itself a finding about the gene and the disease. The quoted sentences say what the papers report.
hepatocellular carcinoma (39 papers, 2009 to 2026). A malignant tumor that arises from hepatocytes. "Several studies have shown that deficiency or downregulation of GNMT is strongly associated with the pathogenesis of hepatocellular carcinoma (HCC), highlighting its critical role as a tumor suppressor." (PMID 41828318, 2026). "Recently, downregulation of GNMT has been considered as a hallmark of hepatocellular carcinoma (HCC)." (PMID 31470507, 2019). "It has been shown that GNMT-deficient mice developed chronic hepatitis, steatosis, and hepatocellular carcinoma (HCC)." (PMID 31470507, 2019). "GNMT downregulation leads to loss of liver function progressing to fibrosis, cirrhosis, and hepatocellular carcinoma." (PMID 30237481, 2018). "We noted that loss-of-function of GNMT by siRNA promoted hepatoma cell growth and migration in comparison with siRNA control." (PMID 27469031, 2016). "Loss of the glycine N-methyltransferase gene leads to steatosis and hepatocellular carcinoma in mice." (PMID 25195642, 2014). "The loss of GNMT in hepatocellular carcinoma may favor the appearance of aberrant DNA methylation patterns on some promoters." (PMID 31208147, 2019). "MiR-224 has also been implicated in the progression of HCV-induced hepatic injury to hepatocellular carcinoma by targeting the 3prime untranslated region of the glycine N-methyltransferase (GNMT) gene and suppressing its expression." (PMID 41465470, 2025). "Immunohistochemical analysis of clinical hepatoma tissue samples revealed that COLEC10, KMO, and GNMT proteins were predominantly localized to the cytoplasm of hepatoma cells in all samples." (PMID 40026364, 2025). "Quantitative reverse-transcription PCR was performed to investigate the expressions of GNMT and c-Myc in both in vitro cultured human hepatoma Mahlavu cells and in vivo hepatocytes from C57BL/6J mice." (PMID 36077467, 2022). "β-PGG was reported to decrease the expression of GNMT in hepatocellular carcinoma by downregulating the expression of Myc." (PMID 35992839, 2022). "The protective role of GNMT has been well characterized in the context of hepatocellular carcinoma and liver fibrosis in mice and in humans." (PMID 36356832, 2022). "We have also evaluated the impact of a potent small molecular inhibitor of hepatocellular carcinoma, 1,2,3,4,6-penta-O-galloyl-β-d-glucopyranoside, which has previously been shown to act in part by upregulating the expression of GNMT." (PMID 33802396, 2021). "It has also been shown that miR-224 can be packaged into exosomes released by hepatocellular carcinoma to regulate cell proliferation and invasion by targeting glycine N-methyltransferase." (PMID 34379706, 2021). "GNMT knockout (GNMT‐/‐) mice display spontaneous hepatic fibrosis and later develop hepatocellular carcinoma." (PMID 32951289, 2020). "Previous studies have indicated that the expression of Glycine N-methyltransferase is inhibited in hepatocellular carcinoma." (PMID 29416626, 2018). "Utilizing CCl4-treated hepatoma cells and mice as a cell damage of inflammatory or liver injury model, we observed that the decreased expression levels of GNMT were accompanied with the elevated expression levels of miR-224 in hepatoma cells and mouse liver." (PMID 30115977, 2018). "Nevertheless, miR-224 cannot completely inhibit GNMT in these liver cancer cell lines suggesting that the downregulation of GNMT is very complex mechanism in hepatoma cells." (PMID 30115977, 2018). "Deletion of GNMT in mice leads to the development of fatty liver, fibrosis and hepatocellular carcinoma as a result of sustained increased levels of SAMe in livers." (PMID 29416626, 2018). "Glycine N-methyltransferase is a tumor suppressor gene for hepatocellular carcinoma, which can activate DNA methylation by inducing the S-adenosylmethionine to S-adenosylhomocystine." (PMID 29416626, 2018).
hepatocellular carcinoma (continued). "It should be noted that GNMT is considered a tumor suppressor of human hepatocellular carcinoma, and the position of the phosphorylated residues in the GNMT tertiary structure is likely to affect the protein’s conformation and activity." (PMID 27357474, 2016). "Glycine N-methyltransferase (GNMT) expression is vastly downregulated in hepatocellular carcinomas (HCC)." (PMID 27153064, 2016). "Purified PL extract and PGG induced GNMT mRNA and protein expression in Huh7 human hepatoma cells and in xenograft tumors." (PMID 27153064, 2016). "It has previously been shown that the glucocorticoid dexamethasone (DEX) is able to activate GNMT in the rat liver and to stimulate its expression in the rat hepatoma cell line H4IIE." (PMID 23997240, 2013). "Additional evidence of the role of GNMT in carcinogenesis came from studies of GNMT knock out mice, which revealed a high tendency to develop hepatocellular carcinomas." (PMID 23936142, 2013). "It was confirmed that both PL and PGG could induce GNMT expression in Huh7 human hepatoma cells and in xenograft tumors." (PMID 38791343, 2024). "GNMT has been proven to have tumor suppression function in hepatocellular carcinoma." (PMID 36467068, 2022). "However, knockout of GNMT in mice leads to spontaneous hepatocellular carcinoma at the age of 8–12 months." (PMID 34203215, 2021). "GNMT is a potential tumor suppressor that is commonly inactivated in human hepatoma." (PMID 28267806, 2017). "Noteworthy is that the health benefits of a concerted upregulation of BHMT-1, MAT-1, and GNMT by betaine treatment could counter their collective downregulation in human hepatocellular carcinoma." (PMID 19239903, 2009). "Moreover, down-regulation of GNMT leads to loss of liver function and progression to fibrosis, cirrhosis and hepatocellular carcinoma, and lack of GNMT aggravates fibrosis caused by cholestasis." (PMID 33241846, 2020). "As shown in clinical hepatocellular carcinoma (HCC) specimens, the expression of GNMT in a tumor was much lower than that in the tumor adjacent area." (PMID 29416626, 2018). "Past studies in rodent models have shown that glycine-N-methyltransferase (GNMT) knockout results in rapid steatosis, fibrosis, and hepatocellular carcinoma progression." (PMID 35216100, 2022). "GNMT expression is significantly downregulated in hepatocellular carcinoma (HCC), and GNMT knockout mice developed HCC, while overexpression of GNMT prevented liver cancer cell proliferation." (PMID 33802396, 2021). "For example, it is down-regulated in almost all hepatocellular carcinoma (HCC); although abundantly expressed in the normal liver, GNMT expression is decreased in HCC tissues." (PMID 30061177, 2018). "GNMT depletion leads to progression of hepatocellular carcinoma (HCC)." (PMID 30217986, 2018). "Isotopic enrichments in the M + 3 species of purines (dA + 3 and dG + 3) were only detected in transformed human hepatoma cell-line without GNMT expression (GNMT−), but not in the GNMT+ cells." (PMID 33233834, 2020). "Expression of GNMT in human hepatoma cells without GNMT helped maintain the methyltransferase activity and possibly maintain DNA methylation." (PMID 33233834, 2020). "Furthermore, DNA hypermethylation represses GNMT gene expression in the pathogenesis of NAFLD and hepatocellular carcinoma." (PMID 31208147, 2019). "ACSL4, GNMT, IFI27, and miR122 are known or expected to play a key role in the clinical courses of HCV-mediated liver diseases by regulating HCV replication and thereby hepatocellular carcinoma." (PMID 30138348, 2018). "Furthermore, GNMT has been shown to be reduced during hepatic injury and multiple genetic analyses of human patients have found that GNMT gene expression is repressed in both NASH and hepatocellular carcinoma patients." (PMID 35216100, 2022).
hepatocellular carcinoma (continued). "Besides, GNMT knockout mice develop chronic hepatitis, glycogen storage disease, steatohepatitis, fibrosis and spontaneous hepatocellular carcinoma (HCC), indicating that GNMT plays an important role in liver function and is a tumor suppressor gene for liver cancer." (PMID 29725048, 2018). "Interestingly, many enzymes involved in SAA metabolism, including MAT1A, GNMT, BHMT, and CBS, are reported to be downregulated in human liver tumors, particularly hepatocellular carcinoma (HCC), the most common and deadly form of liver cancer." (PMID 32770044, 2020). "Finally, NNMT and GNMT did not affect each other’s expression levels in SMMC‐7721 cells, and their mRNA levels were not correlated in hepatoma cell lines." (PMID 31294922, 2019).
liver cancer (22 papers, 2013 to 2025). An epithelial or non-epithelial malignant neoplasm that arises from the liver. "The glycine N-methyltransferase (GNMT) gene functions as a tumor susceptibility gene for liver cancer and exhibits a unique tissue expression pattern." (PMID 38273295, 2024). "GNMT was found to be silent in human liver cancer and down-regulated in the liver of patients at risk of liver cancer, such as hepatitis C virus and alcohol-induced cirrhosis, suggesting its key role in maintaining liver health." (PMID 36139459, 2022). "Therefore, as a tumor suppressor gene for liver cancer, GNMT might be associated with gender disparity in liver cancer susceptibility through its influence on DNA methylation." (PMID 33917049, 2021). "GNMT, which is generally expressed in normal liver tissue, is found to be undetectable in liver cancer and shows attenuated expression in the livers of patients at risk of developing hepatocellular carcinoma." (PMID 38273295, 2024). "This plays an important role in the repression of GNMT, at least in liver cancer, meaning that the changes by the anti-miR-873-5p were expected to be mild." (PMID 35624761, 2022). "GNMT is a tumor suppressor gene in liver cancer, and its high expression can inhibit tumor proliferation." (PMID 36553562, 2022). "The overexpression of GNMT has been shown to prevent aflatoxin-induced carcinogenicity and to inhibit liver cancer cell proliferation." (PMID 30061177, 2018). "The expression of GNMT was significantly lower and that of miR-224 was significantly higher in CCl4-treated liver cancer cell lines and mouse liver tissue than in the control group." (PMID 30115977, 2018). "A dose-dependent repression of GNMT protein expression was detected in all three liver cancer cell lines transfected with 224-mimic." (PMID 30115977, 2018). "Glycine N-methyltransferase (GNMT) is abundantly expressed in the normal liver but is down-regulated in liver cancer tissues." (PMID 27716281, 2016). "GNMT knockout (Gnmt−/−) mice can spontaneously develop chronic hepatitis, fatty liver, and liver cancer." (PMID 27716281, 2016). "High rates of GNMT knockout mice developed HCC, while overexpression of GNMT prevented aflatoxin-induced carcinogenicity and inhibited liver cancer cell proliferation." (PMID 27153064, 2016). "While we cannot offer a suitable explanation of this controversy, our data are very much in-line with reports showing drastically decreased GNMT in more than 80% of prostate cancer tissues as well as in liver cancers." (PMID 23936142, 2013). "Exosomal miR-224 could directly target glycine N-methyltransferase (GNMT), increasing the proliferation and invasion of liver cancer cells." (PMID 35280805, 2022). "Furthermore, GNMT mRNA levels are significantly lower in patients at risk of developing HCC, thus, GNMT has been proposed as a tumor-susceptibility gene for liver cancer." (PMID 36144184, 2022). "Interestingly, we also observed a reduction in the expression of GNMT and a significant inverse correlation between miR-224 and GNMT expression in CCl4-induced inflammation response and oxidative stress of liver cancer cell lines and mice." (PMID 30115977, 2018). "Furthermore, our data indicates that miR-224 plays an important role in tumorigenesis of human liver cancer cells by directly suppressing the GNMT tumor suppressor." (PMID 30115977, 2018). "There is increasing evidence that GNMT plays a crucial role in the pathophysiological features of liver diseases, including chronic hepatitis, glycogen storage, hypercholesterolemia, fatty nodules, and liver cancer." (PMID 27716281, 2016). "Our present results suggest that GNMT is a direct AR target gene in PCa, we suspect that AR signalling may also play an important role in GNMT regulation in liver cancer." (PMID 23883094, 2013).
liver cancer (continued). "Therefore, GNMT plays a crucial role in the pathological process of different liver diseases including chronic hepatitis, glycogen storage, hypercholesterolemia, fatty nodules, and liver cancer." (PMID 30115977, 2018). "In the present study, leveraging GEO liver cancer-related expression data, we identified 42 genes that are commonly downregulated in HCC tissues compared to normal tissues, with COLEC10, KMO, and GNMT being the most frequently altered." (PMID 40026364, 2025). "Conversely, in individuals with liver cancer, the diminished functionality of glycine N-methyltransferase (GNMT) increases the dependency on NNMT for SAM synthesis, given that GNMT is the predominant enzyme accountable for the consumption of SAM." (PMID 40427612, 2025). "It was demonstrated that Glycine N-methyltransferase (GNMT) is downregulated in HCC, and the overexpression of GNMT results in the prevention of AFB1-induced carcinogenicity, together with downgraded liver cancer cell proliferation." (PMID 38791343, 2024). "However, demethylating drug (5-aza-2′-deoxycytidine, DAC) treatment did not lead to significant induction of GNMT mRNA (less than 1.5-fold induction) in liver cancer cell lines." (PMID 30115977, 2018).